ELF2 (E74 like ETS transcription factor 2)
Description:
Isoform 1 transcriptionally activates the LYN and BLK promoters and acts synergistically with RUNX1 to transactivate the BLK promoter. Isoform 2 may function in repression of RUNX1-mediated transactivation.
Synonyms: NERF; EU32; NERF-2; NERF-1A; NERF-1B; NERF-1a,b
Tractability: PROTAC: UniProt records ubiquitination sites on it; ubiquitination databases record sites on it; its protein half-life has been measured.
Gene: Protein-coding gene on chromosome 4 (139,028,112 to 139,177,224, reverse strand). Ensembl gene ENSG00000109381.
Subcellular location: Nucleus
Subcellular location (Human Protein Atlas): Nucleoplasm; Nuclear bodies
Pathways (Reactome):
Gene expression (Transcription): RUNX1 regulates transcription of genes involved in BCR signaling
Gene Ontology:
Molecular function: DNA-binding transcription factor activity, RNA polymerase II-specific; protein binding; sequence-specific double-stranded DNA binding; DNA-binding transcription factor activity; sequence-specific DNA binding
Biological process: positive regulation of DNA-templated transcription; regulation of transcription by RNA polymerase II; cell differentiation; regulation of DNA-templated transcription
Cellular component: nuclear body; nucleoplasm; chromatin; nucleus
Genetic constraint (gnomAD): Loss-of-function variants: 8 observed, 53.19 expected, observed/expected ratio (o/e) 0.15, 90% interval 0.087 to 0.27. The upper end of that interval is the gene's LOEUF score, 0.27, which puts it in group 1 of 6, group 1 being the genes least tolerant of losing a copy. Missense variants: 505 observed, 713.47 expected, observed/expected ratio (o/e) 0.71, 90% interval 0.66 to 0.76. Synonymous variants: 202 observed, 249.89 expected, observed/expected ratio (o/e) 0.81, 90% interval 0.72 to 0.91.
Homologues: Orthologues: chimpanzee ELF2 (100% identical), macaque ELF2 (99% identical), dog ELF2 (98% identical), rabbit ELF2 (94% identical), guinea pig ELF2 (93% identical), mouse Elf2 (92% identical), pig ELF2 (83% identical), rat Elf2 (81% identical), tropical clawed frog elf2 (75% identical), zebrafish elf2b (59% identical). Paralogues in human: ELF1 (34% identical), ELF4 (33% identical), ETV1 (14% identical), ETV5 (14% identical), ELK4 (14% identical), ELK3 (14% identical), ETS1 (13% identical), ETS2 (13% identical), ETV4 (13% identical), ERF (13% identical), ERG (13% identical), FLI1 (12% identical), and 16 more.
Diseases named in the same sentence as ELF2 in open-access papers:
ELF2 is named in the same sentence as 29 diseases in open-access papers, as found by Europe PMC text mining. Sharing a sentence is not in itself a finding about the gene and the disease. The quoted sentences say what the papers report.
hepatoma (3 papers, 2016 to 2022). "In the current study, we focused on the role of ELF2 and mechanisms underlying its regulation by T3/TR in a hepatoma cell line." (PMID 26968954, 2016). "Our findings suggest that stimulation of p21 and p27 in hepatoma cells is mediated via ELF2 repression." (PMID 26968954, 2016). "However, in contrast to these studies, ELF2 overexpression in hepatoma cells actually enhanced tumour cell proliferation, whilst conversely ELF2 knockdown repressed cell growth." (PMID 28351373, 2017). "The results of this study provide new insights into the mechanisms of transcriptional regulation by TRα1: T3-mediated negative regulation of ELF2 may contribute to reduction of hepatoma cell growth through subsequent activation of the cell cycle checkpoint." (PMID 26968954, 2016). "Additionally, ELF2 restored the proliferative ability of hepatoma cells inhibited by T3/TR." (PMID 26968954, 2016).
Ataxia (2 papers, 2018 to 2021). Ataxia refers to impaired coordination of voluntary muscle movement. "In vitro experiments showed that the ELF2 mutation led to an increased expression of Ataxin-2 (SCA2) as well as a reduced expression of ELOVL5 (SCA38), a result establishing links between ELF2-disorder and other ataxia subtypes." (PMID 38835435, 2021). "This work supports that ELF2 gene regulates the expression of ATXN2 and ELOVL5 genes, and defines new molecular links in the pathophysiology of cerebellar ataxias." (PMID 29628936, 2018).
leukemia (2 papers, 2015 to 2016). A malignant (clonal) hematologic disorder, involving hematopoietic stem cells and characterized by the presence of primitive or atypical myeloid or lymphoid cells in the bone marrow and the blood. "Therefore, this new ELF2 variant deserves further study to clarify its possible role in leukemia." (PMID 25590302, 2015). "Moreover, ELF2 physically interacts with acute myeloid leukemia 1 (AML1), a frequent target for chromosomal translocations in leukemia." (PMID 26968954, 2016). "Moreover, ELF2, through interaction with AML1 (acute myeloid leukemia 1) protein, is able to trigger hematopoiesis and in turn is involved in the onset of leukemia." (PMID 25590302, 2015).
cerebral malaria (1 paper, 2021). A sequestration of Plasmodium falciparum in the brain, which can cause coma and/or seizures. "Similarly, the K-TSPs model for cerebral malaria identified nine gene pairs including: TTC17-C18orf8, PUM2-ASB7, RABEP1-MYH11, SETX-SPATS2L, XRCC5-TRIP12, ELF2-CHRNA10, LARP4-ANK2, MREG-KPNA6, and ZNF197-CD53." (PMID 34746025, 2021).
COVID-19 (1 paper, 2023). A disease caused by infection with severe acute respiratory syndrome coronavirus 2. "Interestingly, a recent study also showed downregulation of the elF2 signaling pathway in the transcriptomic analysis of nasopharyngeal swabs derived from COVID-19-infected patients." (PMID 38098019, 2023).
gastric cancer (1 paper, 2025). A primary or metastatic malignant neoplasm involving the stomach. "ETS family members with the highest protein level of expression in many gastric cancer samples include ETV5, ETV4 and ETV3, while ELF2 and ELF3 had moderate to high levels of expression in all samples tested in the Human Protein Atlas but only in one of the two antibodies checked for each protein." (PMID 41425714, 2025).
hereditary ataxia (1 paper, 2018). An instance of an atactic disorder that is caused by an inherited genomic modification in an individual. "The interaction between ELF2,ATXN2, and ELOVL5 genes found suggests that the regulation of expression in these genes could potentially be a shared mechanism in hereditary ataxias." (PMID 29628936, 2018).
lymphoma (1 paper, 2019). A malignant (clonal) proliferation of B- lymphocytes or T- lymphocytes which involves the lymph nodes, bone marrow and/or extranodal sites. "Mutations within ELF2 and HEATR1 were identified in T-cell leukemia/lymphoma patients." (PMID 31046777, 2019).
melanoma (1 paper, 2019). A malignant, usually aggressive tumor composed of atypical, neoplastic melanocytes. "From the ETS family of TFs, ISMARA predicted GABPA, ELF2 and ELF5 with very low significance, while MIPRIP identified ETS1 as a highly significant regulator of TERT in the melanoma samples with a TERT promoter mutation." (PMID 31888467, 2019).
nasopharyngeal carcinoma (1 paper, 2021). A carcinoma arising from the nasopharyngeal epithelium. "In fact, overexpression of ELF2 enhanced tumor cell proliferation in nasopharyngeal carcinoma, while its silencing had the opposite effect." (PMID 33557274, 2021).
neuroblastoma (1 paper, 2018). Neuroblastoma (NB) is the most common solid, extracranial childhood tumor. "We have observed that ELF2 acts as a repressor of ATXN2 gene expression in neuroblastoma cells and that mt-ELF2 will not be likely to regulate its expression." (PMID 29628936, 2018).
osteosarcoma (1 paper, 2017). A usually aggressive malignant bone-forming mesenchymal neoplasm, predominantly affecting adolescents and young adults. "Moreover, ELF2 was up‐regulated in osteosarcoma tissues and negatively associated with miR‐409‐3p levels." (PMID 28286730, 2017). "In clinical osteosarcoma tissues, we also found that increased ELF2 levels in osteosarcoma tissues were negatively correlated miR‐409‐3p expression." (PMID 28286730, 2017). "Taken together, these findings suggest that ELF2 is a direct and functional target of miR‐409‐3p in osteosarcoma." (PMID 28286730, 2017). "Restoration of ELF2 rescued the inhibitory effect of miR‐409‐3p on cell proliferation in osteosarcoma cells." (PMID 28286730, 2017). "In vitro experiments showed that miR‐409‐3p overexpression reduced endogenous ELF2 levels in osteosarcoma cells." (PMID 28286730, 2017). "Together, our data indicate that miR‐409‐3p may be a tumor suppressor in osteosarcoma by targeting ELF2." (PMID 28286730, 2017). "In conclusion, the results obtained in the current study suggest that miR‐409‐3p may function as a tumor suppressor in osteosarcoma, and ELF2 was a direct target of miR‐409‐3p." (PMID 28286730, 2017). "Hence, our findings suggest that ELF2 may be a direct and functional target of miR‐409‐3p in osteosarcoma cells." (PMID 28286730, 2017). "MiR‐409‐3p was down‐regulated, whereas the mRNA and protein expression of ELF2 were up‐regulated in osteosarcoma tissues, compared with their paired ajacent nontumor tissues." (PMID 28286730, 2017). "Additionally, the results show a significant negative correlation between miR‐409‐3p and ELF2 expression in osteosarcoma tissues." (PMID 28286730, 2017). "To explore whether the effect of miR‐409‐3p on osteosarcoma growth is mediated by down‐regulating ELF2 expression, we constructed ELF2 plasmid without 3′UTR and cotransfected with miR‐409‐3p mimics into MG63 cells." (PMID 28286730, 2017). "However, there was no report about whether miR‐409‐3p could directly target ELF2 in osteosarcoma." (PMID 28286730, 2017).
ovarian carcinoma (1 paper, 2023). A malignant neoplasm originating from the surface ovarian epithelium. "For instance, the promoted effect of lncRNA PRNCR1 on the proliferation, migration, and invasion of ovarian cancer was found to be alleviated by the miR-653-5p/ELF2 axis." (PMID 37069939, 2023).
pancreatic cancer (1 paper, 2025). "To assess if ELF2 is enriched at rs13303327 in an allele-preferential manner in the context of the native DNA, we performed chromatin immunoprecipitation followed by quantitative PCR (ChIP-qPCR) in two pancreatic cancer cell lines heterozygous at this SNP (Hs766T and SW1990)." (PMID 40307206, 2025).
retinoblastoma (1 paper, 2025). A malignant tumor that originates in the nuclear layer of the retina. "Together, these findings interrogate the mechanisms underlying topotecan resistance in retinoblastoma and suggest ELF2 as a potential therapeutic target to overcome drug resistance." (PMID 41436498, 2025). "Here, we show that surviving retinoblastoma cells exposed to topotecan showed progressively decreased ELF2 expression, accompanied by reduced apoptosis." (PMID 41436498, 2025). "Importantly, clinical analysis demonstrated a correlation between ELF2 expression and tumor volume in retinoblastoma patients treated with topotecan." (PMID 41436498, 2025).
tumor (12 papers, 2016 to 2025). "Our analysis identified E74-like factor 2 (ELF2), a transcription factor associated with tumor growth, as a direct target downregulated by T3/TR." (PMID 26968954, 2016). "We found modulations in core cellular processes involved in tumor progression, such as anabolism (ElF2 and mTOR signaling) and metabolic control (Sirtuin signaling), in GBM cells exposed to MSC or MSCMel." (PMID 40083939, 2025). "Recent study showed that overexpression of ELF2 enhanced tumor cell proliferation, and conversely, its knockdown suppressed HepG2 cell growth via p21 and p27 activation." (PMID 28286730, 2017). "Overexpression of ELF2 enhanced tumor cell proliferation, and conversely, its knockdown suppressed tumor growth." (PMID 26968954, 2016). "Our findings collectively support a potential role of T3/TR in tumor growth inhibition through regulation of ELF2." (PMID 26968954, 2016). "The observed T3-induced inhibition of cancer cell growth and ELF2 expression supports the hypothesis that T3/TR suppresses tumor proliferation via ELF2 regulation." (PMID 26968954, 2016). "Besides, miR-409 could function as a tumor suppressor in several cancers by targeting zinc-finger E-box-binding homeobox-1 (ZEB1), E74-like factor 2 (ELF2), and GRB2-associated binding protein 1 (GAB1)." (PMID 34338153, 2021). "Further analysis showed that most CNAs, including amplification in AR and deletion in PTEN in P8, amplifications in ELF2 and MYC in P9, and amplifications in MYC and CCND1 in P11, were concordant in the plasma and tumor tissues." (PMID 32631448, 2020). "After depletion of ELF2, proliferation of SK-HEP1 cells was decreased, compared with control cells, confirming the ability of ELF2 to accelerate tumor cell growth." (PMID 26968954, 2016). "Finally, a bovine B-cell/ATL tumour pair had integration sites 17 and 13 kb from the same host gene, respectively (T15, ATL4_2, TMEM67), while an ovine B-cell/ATL tumour pair had their proviruses integrated within and 430 kb downstream of the same host gene, respectively (M395/ATL25_10, ELF2)." (PMID 28534499, 2017).
cancer (7 papers, 2016 to 2025). A tumor composed of atypical neoplastic, often pleomorphic cells that invade other tissues. "Analysis of RNAseq data from 30 cancer studies revealed that ELF2 was more highly expressed in acute myeloid leukaemia (AML) than any other cancer." (PMID 28351373, 2017). "ELF2 is a transcription factor that promotes cancer cell proliferation." (PMID 26968954, 2016). "Moreover, T3-mediated suppression of ELF2 occurred via p21 and p27 activation, leading to inhibition of cancer cell progression." (PMID 26968954, 2016). "We compared the function of ELF2 isoforms ELF2A and ELF2B with other ELF subfamily proteins ELF1 and ELF4 in primary and cancer cell lines using proliferation, colony-forming, cell cycle, and apoptosis assays." (PMID 28351373, 2017). "As the potential role of ELF2 in cancer has not been explored, we analysed ~150 cancer genome sequencing cohorts deposited with The Cancer Genome Atlas (TCGA) and the Catalogue of Somatic Mutations in Cancer (COSMIC) for ELF2 mutations and expression." (PMID 28351373, 2017). "However, 50 transcription factors displayed similar interactions with SWI/SNF in the two cancer types, such as several zinc-finger transcription factors (ZNF512, ZNF598, ZNF609, ZNF687, and ZNF709), CTCF, ELF2, and YBX1, indicating shared gene regulation networks." (PMID 40988026, 2025).
infection (1 paper, 2023). The state of being infected such as from the introduction of a foreign agent such as serum, vaccine, antigenic substance or organism. "For example, elF2 signaling was downregulated in both control and AD cells upon infection." (PMID 38098019, 2023). "However, the IPA of DEGs comparing control infection with the AD infection showed less effective downregulation of the elF2 pathway in the AD OM-ALI cells as compared to control OM-ALI." (PMID 38098019, 2023).
ELF2 also shares sentences with these, for which no sentence is quoted: prostate carcinoma (2 papers); atherosclerosis (1); breast carcinoma (1); cerebellar ataxias (1); CNS tumors (1); Hepatic fibrosis (1); infectious disease (1); multiple sclerosis (1); myeloid malignancies (1); spinocerebellar ataxia 2 (1); T-cell leukemia (1).